HLA-E (major histocompatibility complex, class I, E)
Diseases named in the same sentence as HLA-E in open-access papers (continued):
Sharing a sentence is not in itself a finding about the gene and the disease.
cancer (continued). "The reason for the formation of cellular resistance are immune escape mechanisms of the cancer cells, such as the expression of the non-classical major histocompatibility complex, class I, E (HLA-E) on the cell surface." (PMID 38069020, 2023). "Importantly, NKG2A blockade has an acceptable safety profile in cancer patients and in mice, anti-NKG2A administration led to partial depletion of HLA-E+ hematopoietic cells, but their numbers recovered 7 days post treatment." (PMID 36560403, 2022). "There are classical forms, HLA-A, HLA-B, and HLA-C, and non-classical forms, HLA-G, HLA-E, HLA-F, and HLA-H, of this protein; both have been identified in cancer with diverse roles." (PMID 34359613, 2021). "The non-classical HLA molecule HLA-E is weakly expressed in healthy cervical epithelium while its expression increases with progression to higher stages of cancer." (PMID 30761272, 2019). "This unique property of augmenting the number of CD8+ T lymphocytes and not other lymphocytes by monospecific but not by polyreactive anti-HLA-E mAbs strongly clarifies the potential of the monospecific anti-HLA-E mAbs for passive immunotherapy of cancer." (PMID 31009335, 2019). "Like HLA-E, it is also thought to mediate important immunosuppressive functions, but unlike HLA-G, its significance in cancers is not yet established." (PMID 29587858, 2018). "HLA-E, which binds to the inhibitory CD94/NKG2A receptor expressed by activated NK cells and CD8 T cells, can directly suppress innate and adaptive immunity when expressed by cancer cells." (PMID 26658106, 2016). "When comparing HLA-E positive with HLA-E negative cancer cells, analysis of the top 50 DEGs revealed several cell cycle-related genes that were highly expressed in HLA-E positive cancer cells, including CDKN1A, CDK4, and MDM2." (PMID 40959273, 2025). "In cancer, HLA-E peptides may take advantage of non-classical TAP-independent pathways if the classical ER-based, TAP-dependent route is unavailable." (PMID 39301027, 2024). "Furthermore, in parallel experiments, ImmTAB-inhA molecules did not induce IFN-γ secretion by PBMC in response to a panel of inhA antigen negative cancer cell lines expressing various levels of HLA-E and presenting different sets of endogenous HLA-E ligands." (PMID 38691588, 2024). "Whether NKG2A and NKG2D, which likely have opposing functions with respect to T cell activation, are both concurrently functional is complex, given that the ligands of these receptors (i.e., HLA-E, and MICA/B, ULBP1-6, respectively) can be inducibly expressed in healthy and cancer tissue." (PMID 36796366, 2023). "In addition to direct targeting, the NKG2A:HLA-E axis can also be disrupted indirectly via multiple different targeted cancer agents that were not previously recognised to possess immunomodulatory properties." (PMID 36560403, 2022). "Cancer cell immune evasion can also result from overexpression of HLA-E, even in the absence of HLA-A/B/C molecules and it has been noted that HLA-E may also bind peptides other than canonical leader sequences." (PMID 36560403, 2022). "Although HLA-F has not been studied as intensively as HLA-E and G, increasing body of evidence reveal its clinical relevance in various pathologies including virus infection, pregnancy, autoimmune diseases and cancer." (PMID 34295330, 2021). "However, we notice that HLA genes are amongst the most highly enriched genes in both cancers; furthermore, they are consistently overexpressed in BCC compared to PDAC by a factor of 2-10 with the exception of HLA-E and HLA-F, suggesting that PDAC suffers from much more severe MHC-I suppression." (PMID 35178072, 2021). "In addition, previous data have not conclusively demonstrated the exact roles of Qa-1(HLA-E)-restricted CD8+ T cells in cancers and infections." (PMID 31569411, 2019).
cancer (continued). "Therefore, future clinical applications of HLA-E-restricted CD8+ T cells in infections and cancers will depend on whether the preclinical paradoxical findings can be fully understood." (PMID 31569411, 2019). "However, this was not a consistent effect in all HPV+ carcinomas, as HLA-E was expressed at much higher levels in the HPV+ samples compared with the HPV− samples in the CESC cohort." (PMID 28891951, 2017). "Interestingly, the authors showed that their cancer vaccine could trigger an HLA-E-restricted CD8+ T cells response to non-canonical epitopes, including a peptide encoded by prostatic acidic phosphatase (PAP)." (PMID 39301027, 2024). "HLA-G or HLA-E could be valuable enhancers of immune responses in other cancers and for NK-cell targeted strategies, as shown for the anti-NKG2A blocking antibody monalizumab now developed as a novel first-in-class checkpoint inhibitor for HLA-E-positive cancers." (PMID 34201079, 2021). "TCRγδ+ T cells, which usually expand in response to cancer or chronic infections such as cytomegalovirus, showed a similar cytotoxic activity than NK cells, as well as the ability to recognize cells with missing-self and antigens presented by HLA-E or even without previous antigen processing." (PMID 34122423, 2021). "Cancers can also evade immune elimination by expressing non-classical MHC class I molecules (MHC Ib), such as HLA-E and HLA-G." (PMID 35892842, 2022). "Development of antibodies which specifically recognise HLA-E epitopes and do not bind other HLA classes has been achieved and these have been shown to enhance NK cell and CD8+ T cell cytotoxicity against cancer targets." (PMID 36560403, 2022). "A recent study investigating immune evasion mechanisms by genome-scale in vivo CRISPR screens across cancer models treated with ICB identified immune evasion genes and immunosuppressive checkpoints conserved across cancers, including the non-classical MHC class I molecule Qa-1b/HLA-E." (PMID 37492581, 2023). "Additionally, they described negative feedback suggesting that HLA-E on tumor cells and its receptors on CD8+ T cells can be induced via cancer vaccines." (PMID 38041084, 2023). "This study demonstrated that miR-19a or miR-19b-1 overexpression in cancer cells led to a general downward trend in the expression profile of MHC Class I molecules (such as HLA-B, HLA-E, HLA-F, HLA-G or HLA-J), which has never been reported in other physiological and pathological processes." (PMID 32308549, 2020). "Virally infected and cancer cells manage to escape the immune responses by the negative control of classical MHC but also by the regulation and shedding of class Ib MICA, MICB and HLA-E." (PMID 32887413, 2020). "Similarly, higher or comparable levels of expression of the non-classical genes, HLA-E, HLA-F, and HLA-G, were observed in HPV+ cancers with respect to normal control tissues in the HNSC cohort." (PMID 28891951, 2017). "The level of HLA-E expression and presence or absence of KIR ligands in germline tissue will determine the educational environment and subsets of NK cells that are trained to react to perturbed expression of HLA on tumors, which has been shown to vary extensively across cancers." (PMID 31623687, 2019). "Since the commercial anti-HLA-E mAbs, particularly those most commonly used on human cancer tissues such as MEM-E/02 and 3D12, do not meet the critical requirement of monospecificity of the mAb, they may not be considered reliable for specific immunorecognition of HLA-E on human cancer tissues." (PMID 31009335, 2019).
infection (77 papers, 2009 to 2025). The state of being infected such as from the introduction of a foreign agent such as serum, vaccine, antigenic substance or organism. "HIV-1 active infection has been reported to cause significant downregulation of surface HLA-E levels, which serves as a marker for NK-cell targeting." (PMID 40143326, 2025). "This is the case of an interesting study on high-risk human papillomavirus, whose infection is able to repress HLA-E expression through methylation alteration." (PMID 30718669, 2019). "HLA‐E mismatching has also been correlated with the risk of GvHD and infection." (PMID 40764252, 2025). "However, there are concerns about vaccinating with a vector that causes lifelong infection and difficulty in inducing HLA-E and MHC class II CD8 T cell-restricted responses in humans." (PMID 31413132, 2019). "Of note, the two identified HLA-E alleles are HLA-ER and HLA-EG, but the HLA-ER/HLA-ER homozygous genotype appears to be associated with increased resistance to infection or spontaneous resolution of HCV infection, resulting in an abundance of the permissive HLA-EG in HCV patients." (PMID 28769934, 2017). "However, in times of cellular stress or infections, HLA-E is associated with a much more diverse repertoire of peptides, which can be sensed directly by αβ TCR." (PMID 23226431, 2012). "Therefore, CMV-associated HLA-E restricted T cells could account for the well-established association between CMV-infection and accelerated allograft rejection." (PMID 23226431, 2012). "In our setting, HLA‐E expression was low and infection led to a further reduction due to the activity of immune evasins and the absence of an HLA‐E stabilizing peptide in the UL40 protein of our TB40 strains." (PMID 39931744, 2025). "HLA‐E also modulates CD8+ T cell responses against infections like CMV and HIV by presenting a more diverse repertoire of viral peptides via TAP‐independent pathways that bypass CMV mediated TAP inhibition." (PMID 40764252, 2025). "HLA‐E, the ligand of the heterodimers CD94/NKG2A and CD94/NKG2C, showed generally low expression in uninfected HFF and infection with all variants led to further downregulation, indicating activity of immune evasins within the US2‐US11 region." (PMID 39931744, 2025). "Specific alloreactive T‐cell responses to signal peptides presented by HLA‐E are detectable in some individuals, being attributable to infection by a HCMV strain displaying a UL40‐derived peptide different from host HLA‐I signal sequences." (PMID 40347012, 2025). "Under pathological conditions, such as infections or tumors, HLA-E expression is, however, often upregulated in most tissues." (PMID 41283666, 2025). "In most infections, T cell responses to HLA-E-bound peptides are rare compared to those recognising peptides presented by classical MHC Ia molecules, but exceptions are known." (PMID 38571959, 2024). "When monitoring HLA-E surface expression post infection, we found that the SARS-CoV-2 BQ.1 variant induced lower HLA-E levels compared to ancestral SARS-CoV-2." (PMID 39652590, 2024). "The continuous expression of HLA-E upon infection has sparked interest in identifying and targeting MHC-E-associated epitopes for vaccine strategies against other viruses." (PMID 39301027, 2024). "For instance, in the context of pathogen infections, a recent study described a TCR-based bispecific molecule that potently and selectively binds HLA-E in complex with a peptide encoded by the inhA gene of Mtb." (PMID 39301027, 2024). "Our findings propose that the presence of dysfunctional HCMV-specific HLA-E-restricted CD8 T cells together with post-infection changes in the immune cell distribution affecting NK and γδT cells defines an early immune signature for CLAD in HCMV+ LTRs." (PMID 37187736, 2023).
infection (continued). "The findings provide a better understanding of how HLA-E is elegantly regulated to achieve its immunological functions and give insight into HLA-E’s relative resistance to surface downregulation during infections." (PMID 37140910, 2023). "This study quantified and phenotyped conventional (HLA-A2pp65) and HLA-E-restricted (HLA-EUL40) anti-HCMV CD8+ T (CD8 T) cell responses induced by infection in LTRs developing CLAD or maintaining a stable allograft." (PMID 37187736, 2023). "Our findings shed light on the potential mechanisms by which HLA-E is relatively resistant to surface downregulation during infection." (PMID 37140910, 2023). "The HLA-E soluble circulating isoform (sHLA-E) results from the shedding of membrane bound HLA-E molecules, which can be induced by stressful events, such as infection or inflammation." (PMID 35806227, 2022). "Our results are further supported by previous studies that have suggested different effects of HIV viremia on NK cell number and function during either acute or chronic stages of the infection in a HLA-E dependent manner." (PMID 36466823, 2022). "The heterodimer NKG2C:CD94 binds to the non-classical major histocompatibility complex (MHC) class I molecule HLA-E in humans or Qa-1 in mice and is highly expressed on a subset of NK cells found upon infection with the human cytomegalovirus." (PMID 34445750, 2021). "Given such pivotal functions, especially in NK-cell-mediated immuno-surveillance, the HLA-E loci has been extensively studied both at genetic and/or expression levels in various immune-related pathologies, including infections, inflammation and autoimmunity." (PMID 34642395, 2021). "HLA-E molecules also exist as a soluble circulating isoform, soluble HLA-E (sHLA-E), which result from the shedding of membrane bound HLA-E molecules induced by stressful events, such as infections and/or inflammation." (PMID 34642395, 2021). "Upregulation of total HLA class I is dependent on active viral replication and is mediated in part by cytokines and other soluble factors induced by infection, while upregulation of HLA-E occurs in the presence of replication-incompetent virus." (PMID 31396492, 2019). "Further, HLA-E tetramers have identified Mtb peptide-specific CD8+ T cells in PBMCs of TB patients at the highest frequency during active infection, suggesting that HLA-E constitutes an important element in Mtb immunity." (PMID 28475642, 2017). "Although CD8+ T cells can recognize Mtb-infected cells via HLA-E, little is known about the ligand(s) that are processed and presented for HLA-E in the context of intracellular infection." (PMID 29176828, 2017). "Although HLA-E is known to present pathogen-derived antigens from bacterial pathogens including Mtb, specific ligands generated during infection remain largely unidentified." (PMID 29176828, 2017). "Although we identified 28 Mtb peptides bound to HLA-E in the context of infection, these peptides were a very small proportion (0.4%) of the ligand pool." (PMID 29176828, 2017). "The goal of this study was to characterize the ligandome displayed by HLA-E following infection with Mycobacterium tuberculosis (Mtb) using an in-depth mass spectrometry approach." (PMID 29176828, 2017). "Further analysis of the T cells elicited through recognition of these peptides will increase our understanding of the HLA-E-restricted cellular response to infection with Mtb." (PMID 29176828, 2017). "TFH are expanded in HIV and SIV infection, upregulate HLA-E upon HIV infection, and constant antigenic stimulation occurs in the follicle and GC." (PMID 27716848, 2016). "Considering HLA-E and pathogen infections, HLA-E can bind to different viral peptides derived from CMV, the Epstein-Barr virus, the human immunodeficiency virus, the influenza virus, and Hepatitis C virus." (PMID 27493971, 2016).
infection (continued). "While infection with HCMV resulted in a significant decrease in HLA-E expression, only small effect was observed for the expression of classical HLA-A,-B,-C." (PMID 23592985, 2013). "Provided that NKG2C is functionally involved in the antiviral immune responses, in some infections the upregulation of the ligand, HLA-E, would provide a straightforward explanation for the expansion of NK cells carrying its cognate receptor NKG2C." (PMID 24086127, 2013). "Among the three cell lines, induction of the HLA-E gene in HFF was maximal (3.2 fold) at 30 h after infection (Table." (PMID 24236107, 2013). "In contrast, JEV-infected HFF cells showed a perceptible increase in cell surface expression of both total HLA (-A, -B and -C) and HLA-E despite its limited ability to support infection." (PMID 24236107, 2013). "Future studies need to dissect this “primordial” host immune response pathway, and to determine the relative importance of effector vs. immunoregulatory activities within the HLA-E based antigen presentation system in infection and other human diseases." (PMID 20195504, 2010). "Furthermore, a recent report has shown that infection with SARS-CoV-2 leads to increased HLA-E expression in lung cells, which in turn results in enhanced degranulation, IFNγ production and target cell cytotoxicity in NKG2C+ adaptive-like NK cells." (PMID 40358152, 2025). "The route of administration for mucosal BCG vaccination and Mtb challenge in RMs was similar, but only Mtb increased frequencies of HLA-E–Mtb CD4+ and CD8+ T cells, suggesting that differences in the infection cycle or virulence influenced the capacity to induce HLA-E–Mtb-restricted T cells." (PMID 39460296, 2024). "Thus, in LTRs developing CLAD, there is a possible trend toward a decrease in HCMV-specific CD8 T-cell responses post-infection including a selective decrease in HLA-E-restricted CD8 T-cell responses." (PMID 37187736, 2023). "Intriguingly, among recipients who developed CMV infection after HSCT, a higher HLA-E T (*01:01) allele frequency was noted when compared with those without the infection (67.65% vs. 53.03%, p = 0.050)." (PMID 37351346, 2023). "The typical low surface expression of HLA-E may prevent or limit natural HLA-E–restricted T cell priming in most infections, making prior immune escape unlikely and facilitating the therapeutic application of HLA-E–restricted T cells." (PMID 37140910, 2023). "HLA-E-restricted UL40-specific CD8T cell responses appear early after HCMV primary infection and represent a stable pool of HCMV-specific CD8T cells representing 1-to-4% (median values), according to hosts, of total circulating CD8T cells that maintain for life." (PMID 36532017, 2022). "We found that HLA-E-restricted CD8T are almost as frequent as the « immunodominant » conventional HLA-A2-restricted pp65-specific CD8T responses early after a primary infection as well as decades post-infection, during viral latency." (PMID 36532017, 2022). "MHC variants showed no important associations between class I antigen-presentation genes (HLA-A, HLA-B, and HLA-C) and nonclassical HLA class I genes (HLA-G, HLA-E, and HLA-F) in symptomatic infection susceptibility." (PMID 34650566, 2021). "HLA‐E can also restrict non‐canonical CD8+ T cells during natural infection with various pathogens, although the extent to which they are involved in pathogen control is mostly unknown." (PMID 30968409, 2019). "Given the critical role that endothelial cells play in the pathogenesis of DENV, we wanted to determine whether infection with DENV altered the expression of MHC class I related genes including HLA‐E." (PMID 30263117, 2018). "Since immunosuppressed lung transplant patients are particularly sensitive to infection and HLA sensitization, we speculated that HLA-E genotype could have an influence on the lung protection/allograft rejection balance." (PMID 27493971, 2016).